RETN (resistin)
Diseases named in the same sentence as RETN in open-access papers (continued):
Sharing a sentence is not in itself a finding about the gene and the disease.
Insulin resistance (continued). "Several studies support the positive relationship between insulin resistance and elevated plasma resistin levels in obese and type 2 diabetic individuals, whereas other studies have shown contradictory findings." (PMID 30906281, 2019). "Considering that both TNF-α and resistin confer insulin resistance, CAPE seems to interfere with obesity-induced insulin resistance." (PMID 31805752, 2019). "Higher resistin mRNA levels have been detected in the subcutaneous adipose tissue of obese, post-menopausal women; these levels also correlated positively with body mass index (BMI), serum resistin concentrations, and insulin resistance." (PMID 31533709, 2019). "Supporting their study, we have found a reduction in resistin levels, despite the finding indicating that a five-month treatment of isotretinoin is related with insulin resistance in our study." (PMID 30761880, 2019). "The overall analysis revealed a positive correlation between resistin levels and insulin resistance (r = 0.21, 95% CI: 0.06–0.35); however, heterogeneity (I2 = 59.7%, P = 0.003) remained significant." (PMID 31803062, 2019). "It seems, therefore, that the lowering of adiponectin, leptin and resistin concentrations obtained following liposuction and the reduction of insulin resistance markers can be assessed as its positively modulating effects on fat metabolism." (PMID 31500356, 2019). "Using BNL CL.2 cells, we investigated the effect of resistin in untransfected or CAP1 siRNA-transfected cells on the expression of 84 key genes involved in insulin resistance." (PMID 31294061, 2019). "A recent report also indicated that isothiocyanate-rich Moringa oleifera extract reduced weight gain, insulin resistance, and hepatic gluconeogenesis in mice by reducing plasma insulin, leptin and resistin." (PMID 31220177, 2019). "As its name expresses, resistin appears to have a role in insulin resistance, but some evidence on this issue is paradoxical and hard to explain." (PMID 30886868, 2019). "As it is known, adiponectin enhances insulin sensitivity, resistin increases insulin resistance, and leptin has anorexigenic activity." (PMID 30996303, 2019). "•We found that resistin modulates gene expression of several genes related to insulin resistance, and the effect of some of these genes is modulated by CAP1." (PMID 31294061, 2019). "In the present meta-analysis, we found that resistin levels are correlated with insulin resistance in obese and T2DM patients, and this correlation was associated with resistin levels." (PMID 31803062, 2019). "It is well known that resistin regulates glucose metabolism in mammalians and that high levels of circulating resistin are responsible for insulin resistance." (PMID 31772701, 2019). "In contrast, resistin, another adipocyte-secreted hormone, induces insulin resistance and hypothalamic leptin insensitivity and strongly increases circulating leptin concentrations in transgenic mice with moderate adipocyte-specific resistin overexpression." (PMID 31514318, 2019). "It has been reported that infusion of resistin in rodents aggravated hepatic glucose production, and triggered severe hepatic insulin resistance." (PMID 31208019, 2019). "Some studies have shown that resistin affects glucose transport and causes insulin-stimulated insulin receptor substrate-1 (IRS-1) degradation leading to insulin resistance induction." (PMID 31236417, 2019). "Several adipokines like resistin, adiponectin, lipokolin-2 and IL-6 contribute to the development of insulin resistance, type 2 diabetes and cardiovascular diseases." (PMID 30674322, 2019). "There have also been several studies failing to find a significant correlation between resistin levels and insulin resistance in diabetic groups." (PMID 31803062, 2019). "In human studies, individuals with severe insulin resistance had higher resistin levels than individuals with normal insulin action." (PMID 31803062, 2019).
Insulin resistance (continued). "The leptin-to-adiponectin ratio (LAR) is used to assess insulin resistance among type-2 diabetes mellitus patients and healthy individuals, while resistin levels were found to correlate with insulin resistance in septic patients." (PMID 31540528, 2019). "Recombinant resistin triggered systemic insulin resistance in mice and decreased insulin-mediated glucose uptake in adipocytes." (PMID 31208019, 2019). "Nevertheless, subgroup analysis suggested that circulating resistin levels were significantly positively correlated with insulin resistance in individuals with hyperresistinemia (≥14.8 ng/ml) (r = 0.52, 95% CI: 0.35–0.68, I2 = 0.0%, P = 0.513)." (PMID 31803062, 2019). "Some authors believe that in humans, resistin plays a more important role in inflammatory processes than in insulin resistance, as serum resistin levels correlate better with subclinical inflammation than with insulin resistance." (PMID 30809105, 2019). "Overexpression of resistin in metabolically healthy mice led to insulin resistance and dysregulated lipid metabolism with increased accumulation of triglycerides and cholesterol." (PMID 30353146, 2018). "First identified in murine adipocytes as a secreted protein capable of inducing insulin resistance, resistin is a pro-inflammatory adipokine that induces the secretion of TNFα and IL-6 from various cell types including PBMCs and pancreatic acinar cells." (PMID 29760587, 2018). "This is consistent with our results, which showed a positive correlation between the circulating resistin level and the indicator of insulin resistance HOMA-IR in elderly patients with T2DM." (PMID 29848323, 2018). "In this regard, the hormone resistin, acting through the CNS, has been demonstrated to promote both peripheral and hypothalamic insulin resistance, impairing energy homeostasis." (PMID 29500410, 2018). "This is in agreement with the marked reduction in the circulating levels of NEFA, resistin and leptin observed in RNAi treated rats, whose high levels were positively correlated with adiposity, insulin resistance, diabetes and metabolic syndrome." (PMID 29500410, 2018). "Insulin resistance has recently been reported to increase FGF23 levels, and resistin is a peptide that mainly regulates insulin resistance." (PMID 30228288, 2018). "We have previously demonstrated that resistin promotes cardiac hypertrophy and insulin resistance through inhibition of AMP-activated protein kinase (AMPK) activity." (PMID 30353146, 2018). "It should be a limitation for our study, although several studies have shown that there are conserved biological effects of resistin across the species such as insulin resistance." (PMID 30416448, 2018). "Adiponectin is the most important factor for increasing insulin sensitivity, while factors including leptin, resistin and C-reactive protein are known to be correlated with the increase of insulin resistance." (PMID 29793496, 2018). "Latterly, resistin has received a great deal of attention because of its role in insulin resistance and type 2 diabetes." (PMID 29584687, 2018). "Since, resistin acts through peripheral and central pathways promoting insulin resistance and affecting overall energy homeostasis, we decided to analyse the role of central s-resistin in whole-body physiology." (PMID 29500410, 2018). "Animal studies suggest that the role of resistin in the pathophysiology of type 2 diabetes mellitus is through inflammation-induced insulin resistance." (PMID 29138754, 2017). "This study in rodents showed that resistin is primarily produced in adipose tissue and/or by adipocytes and is involved in insulin resistance." (PMID 28758929, 2017). "In humans, resistin is present in two quaternary forms: an abundant high molecular weight hexamer and a less abundant but more bioactive trimer, which induces hepatic insulin resistance and inflammation." (PMID 28490838, 2017).
Insulin resistance (continued). "The expanded abdominal fat mass will result in insulin resistance through increased production of the adipokine, resistin." (PMID 28451029, 2017). "The initial discovery of resistin suggested a major role for this mediator in diabetes and insulin resistance." (PMID 28758929, 2017). "Resistin is mainly expressed in macrophages from adipose tissue and is considered to contribute to insulin resistance and inflammation, while adipsin, also known as Factor D, is a key component of the alternative complement pathway." (PMID 28491119, 2017). "Bariatric surgery results in a significant reduction in resistin levels at 12 months which correlates with insulin resistance." (PMID 29187850, 2017). "The adipocyte-derived hormones leptin, adiponectin, and resistin are known to play an important role in the development of insulin resistance, the main pathologic mechanism of many metabolic and vascular diseases." (PMID 28448547, 2017). "Adiponectin plays an important role in protecting against insulin resistance and inflammation, whereas leptin and resistin have the opposite effects." (PMID 28448547, 2017). "In mice fed a high fat diet, normalization of resistin levels by antisense oligonucleotides reverses hepatic insulin resistance." (PMID 28661458, 2017). "In abdominal obesity, visceral adipocytes produce several adipocytokines, such as adiponectin, resistin, and leptin, which increase insulin resistance." (PMID 28775758, 2017). "Adiponectin has anti-inflammatory actions and its plasma levels are inversely correlated to insulin resistance, whereas resistin enhances insulin resistance, and has pro-inflammatory actions." (PMID 28824543, 2017). "The adipokines including leptin, adiponectin, visfatin and resistin have a role in insulin resistance in obese subjects and there is a significant relation between insulin resistance and obesity." (PMID 27891497, 2016). "In the same context, MIF stimulates the inflammatory adipocytokines; resistin and IL-6 both are key molecules in the development of insulin resistance." (PMID 27298517, 2016). "Administration of recombinant resistin in rodents has been shown to impair insulin sensitivity, and treatment with anti-resistin antisense oligonucleotides has been shown to reverse insulin resistance." (PMID 26811539, 2016). "Our previous studies showed that Hcy contributes to insulin resistance by inducing endoplasmic reticulum stress, upregulating the expression of resistin, and interrupting the phosphorylation of insulin receptor tyrosine kinase." (PMID 26758372, 2016). "The contribution of serum adiponectin and resistin as biomarkers of insulin resistance and development of the metabolic syndrome among women with PCOS has been a matter of debate during the last years." (PMID 28546817, 2016). "Resistin is a mediator of insulin resistance and is also known as ADSF (ADipocyte-Secreted Factor) or FIZZ3 (found in inflammatory zone 3)." (PMID 27721574, 2016). "Resistin is a newly identified adipokine that has been suggested to play a role in the development of insulin resistance." (PMID 26811539, 2016). "A number of these adipokines, such as adiponectin, leptin, TNF-α, resistin, PAI-1, IL-6 and MCP-1, were found to be directly related to insulin resistance and associated morbidities." (PMID 27651836, 2016). "It has been reported that insulin sensitivity can be reduced by stimulating the secretion of free fatty acids, tumor necrosis factor α, and resistin from enlarged adipocytes, and there is a correlation between insulin resistance and the visceral fat load." (PMID 26767080, 2016). "This suggests that resistin is a key player on the induction of insulin resistance and it is closely related to it." (PMID 26862350, 2016). "Increasing evidence indicates that resistin plays an important regulatory role in addition to its role in insulin resistance in cardiovascular disease." (PMID 26811539, 2016).
Insulin resistance (continued). "The name resistin (RES) of this adipokine has been derived from the observation that it induced insulin resistance in mice." (PMID 26783391, 2015). "In contrast, elevated resistin has been proposed to increase insulin resistance, and the repression of resistin expression in normal mice by PPARγ agonists is thought to enhance insulin sensitivity." (PMID 25951943, 2015). "Several adipokines including leptin, visfatin, adiponectin and resistin are reported to be involved in development of insulin resistance." (PMID 25945322, 2015). "Initial studies in rodent animal models suggested that resistin involves in insulin resistance and T2D." (PMID 25945322, 2015). "This study showed significant reduction in waist circumference, insulin resistance, and serum resistin following a dietary control program." (PMID 25784935, 2015). "Agents that cause insulin resistance, such as TNF-α, have been shown to negatively regulate the expression and secretion of resistin, although paradoxically, studies have shown a contradictory increase in levels of resistin in response to TNF-α." (PMID 26097512, 2015). "Serum leptin, resistin, and lipocalin are increased in psoriasis patients and have a potential important role for developing insulin resistance and cardiovascular disease in psoriasis." (PMID 26339139, 2015). "While originally described as an adipocyte-specific hormone modulating insulin resistance in rodents, it is imperative to note that there are marked differences in the source of production of resistin between humans and rodents." (PMID 25918482, 2015). "It has also been reported that increased serum resistin levels in obese patients with insulin resistance and resistin impair glucose homeostasis and insulin action in mice." (PMID 26681840, 2015). "Two adipokines (adiponectin and resistin) have opposite relations with insulin resistance and inflammation." (PMID 26703679, 2015). "Although resistin was first postulated to contribute to insulin resistance, it has recently been shown that resistin can trigger a proinflammatory state." (PMID 25838618, 2015). "Plasma adiponectin is a strong anti-inflammatory marker whereas plasma resistin is positively related to inflammation and insulin resistance." (PMID 26703679, 2015). "Our study analyzed the effects of miR-492 on insulin resistance, endothelial activation, and resistin expression in apoE knock-out mice and human umbilical vein endothelial cells after high-glucose treatment and miR-492 mimics transfection." (PMID 24526524, 2014). "Some authors previously demonstrated a correlation between resistin plasma levels and insulin resistance in lipodystrophic HIV patients and others in HIV patients either with or without lipodystrophy." (PMID 24958357, 2014). "All of these findings clearly suggest a pivotal role of resistin in insulin resistance and type 2 diabetes, although the receptor and relevant intracellular signaling pathway of resistin have not yet been completely understood." (PMID 24692844, 2014). "Taken together, we newly found that there was an inverse relationship between miR-492 and resistin in apoE-null mice with pre-atherosclerosis pathological changes and insulin resistance." (PMID 24526524, 2014). "Experimental mice models have shown that recombinant resistin promotes insulin resistance and decreases insulin-stimulated glucose transporters in adipose tissue, while antiresistin antibodies produce the opposite effect." (PMID 24741627, 2014). "In order to further consolidate the regulatory relationship between miR-492 and resistin in insulin resistance, the expression of miR-492 and resistin in 3T3-L1 adipocytes treated with insulin were detected." (PMID 24526524, 2014). "Knockdown of resistin can completely reverse the hepatic insulin resistance in diet-induced insulin resistant mice." (PMID 24692844, 2014).
Insulin resistance (continued). "In animal models, resistin also regulates glucose and lipid metabolism in the liver and acts as a mediator of hepatic insulin resistance." (PMID 24733068, 2014). "Resistin was initially named after its ability to evoke insulin resistance in rodents, but in humans the relation between resistin and insulin resistance or BMI is less clear." (PMID 25333960, 2014). "Adipocytes secrete substances that contribute to peripheral insulin resistance, including adiponectin, resistin, TNF-alpha and interleukin 6 which interfere with glucose metabolism and exert lipotoxic effects on pancreatic beta cells." (PMID 25374160, 2014). "The increased expression of resistin in mRNA, and protein levels were observed in insulin resistance hepatocytes or peripheral blood mononuclear cells in female patients with diabetes mellitus type 2 compared with healthy women." (PMID 24526524, 2014). "The role of resistin in insulin resistance was also investigated in mice, engineered to knockdown or overexpress resistin." (PMID 24692844, 2014). "Several studies have consistently reported a close relationship between resistin levels and obesity, insulin resistance, or type 2 diabetes." (PMID 24733068, 2014). "The development of atherosclerosis (AS) is a multifactorial process, in which elevated plasma resistin (a key factor leading to insulin resistance) levels play an important role." (PMID 24526524, 2014). "Despite elevated resistin levels in GDM, the independent relationship between insulin resistance and circulating resistin concentrations cannot be established." (PMID 25202741, 2014). "To date, a range of adipokines (e.g., IL-6, TNF-α and resistin) have been reported to promote insulin resistance in adipocytes through the STAT3-SOCS3 pathway." (PMID 24516630, 2014). "In our results, we have observed that Carassius auratus complex formula treatment significantly downregulated resistin expression in parallel with decreased abdominal adiposity and reduced insulin resistance." (PMID 24511320, 2014). "Mouse resistin, a cysteine-rich protein primarily secreted from mature adipocytes, is involved in insulin resistance and type 2 diabetes." (PMID 24692844, 2014). "In the present study, we evaluated the association between 4 insulin resistance genes (ADIPOQ, LEPR, RETN, and TRIB3) and both T2DM and hypertension." (PMID 24414038, 2014). "Together, our findings indicate that miR-492 contributes to insulin resistance and endothelial dysfunction induced by high glucose, via directly downregulating resistin expression, and involving STAT3 phosphorylation, SOCS, and P-selectin activation." (PMID 24526524, 2014). "Of particular note is resistin, a hormone that links inflammation, insulin resistance and coronary heart disease, which is down-regulated more than 10-fold in GK rats." (PMID 24205240, 2013). "The design of the study was conducted so that to find the role of resistin in the generation of insulin resistance, including subjects with newly found OSA." (PMID 23497617, 2013). "Proinflammatory cytokines such as resistin, tumour necrosis factor alpha (TNF-α), interleukin (IL)-6, and IL1β are widely acknowledged as important pathophysiological factors implicated in insulin resistance." (PMID 24224165, 2013). "Resistin is an inflammatory cytokine that plays a role in the regulation of glucose metabolism and several studies have suggested that resistin leads to insulin resistance in vivo." (PMID 23762167, 2013). "The heart is thought to be a resistin target where it enhances phosphorylation of insulin receptor substrate-1 and thus insulin resistance, impacting glucose transport." (PMID 24205240, 2013). "Acute administration of recombinant resistin to rats results in impaired glucose tolerance and hepatic insulin resistance." (PMID 24288561, 2013).